TDP2 (tyrosyl-DNA phosphodiesterase 2)
Description:
DNA repair enzyme that can remove a variety of covalent adducts from DNA through hydrolysis of a 5'-phosphodiester bond, giving rise to DNA with a free 5' phosphate. Catalyzes the hydrolysis of dead-end complexes between DNA and the topoisomerase 2 (TOP2) active site tyrosine residue. The 5'-tyrosyl DNA phosphodiesterase activity can enable the repair of TOP2-induced DNA double-strand breaks/DSBs without the need for nuclease activity, creating a 'clean' DSB with 5'-phosphate termini that are ready for ligation. Thereby, protects the transcription of many genes involved in neurological development and maintenance from the abortive activity of TOP2. Hydrolyzes 5'-phosphoglycolates on protruding 5' ends on DSBs due to DNA damage by radiation and free radicals. Has preference for single-stranded DNA or duplex DNA with a 4 base pair overhang as substrate. Acts as a regulator of ribosome biogenesis following stress. Also has 3'-tyrosyl DNA phosphodiesterase activity, but less efficiently and much slower than TDP1. Constitutes the major if not only 5'-tyrosyl-DNA phosphodiesterase in cells. Also acts as an adapter by participating in the specific activation of MAP3K7/TAK1 in response to TGF-beta: associates with components of the TGF-beta receptor-TRAF6-TAK1 signaling module and promotes their ubiquitination dependent complex formation. Involved in non-canonical TGF-beta induced signaling routes. May also act as a negative regulator of ETS1 and may inhibit NF-kappa-B activation. (Microbial infection) Used by picornaviruses to remove the small polypeptide, VPg (virus Protein genome-linked, the primer for viral RNA synthesis), from the genomic RNA of the virus. Acts as a 5'-tyrosyl RNA phosphodiesterase and cleaves the covalent VPg-Tyr-RNA bond. This cleavage would play a role in viral replication and occur in viral replication vesicles, but would not act on viral mRNA.
Synonyms: hTDP2; EAPII; EAP2; TTRAP; AD022; dJ30M3.3
Tractability: Small molecule: a structure with a bound ligand is known; a high-quality ligand is known. PROTAC: UniProt records ubiquitination sites on it; ubiquitination databases record sites on it; its protein half-life has been measured; a small molecule that binds it is known.
Target class: Enzyme; Phosphodiesterase
Gene: Protein-coding gene on chromosome 6 (24,649,978 to 24,666,930, reverse strand). Ensembl gene ENSG00000111802.
Subcellular location: Nucleus; Nucleus, PML body; Nucleus, nucleolus; Cytoplasm
Subcellular location (Human Protein Atlas): Nuclear bodies; Nucleoplasm
Pathways (Reactome):
DNA Repair: Nonhomologous End-Joining (NHEJ)
Gene Ontology:
Molecular function: 5'-tyrosyl-DNA phosphodiesterase activity; magnesium ion binding; manganese ion binding; protein binding; single-stranded DNA binding; tyrosyl-RNA phosphodiesterase activity; transcription corepressor activity; catalytic activity; DNA binding; tyrosyl-DNA phosphodiesterase activity
Biological process: double-strand break repair; neuron development; cell surface receptor signaling pathway; negative regulation of DNA-templated transcription
Cellular component: cytoplasm; nuclear body; nucleoplasm; nucleus; PML body; nucleolus
Genetic constraint (gnomAD): Loss-of-function variants: 32 observed, 35.91 expected, observed/expected ratio (o/e) 0.89, 90% interval 0.67 to 1.2. The upper end of that interval is the gene's LOEUF score, 1.2, which puts it in group 5 of 6, group 1 being the genes least tolerant of losing a copy. Missense variants: 361 observed, 378.28 expected, observed/expected ratio (o/e) 0.95, 90% interval 0.88 to 1.04. Synonymous variants: 152 observed, 134.81 expected, observed/expected ratio (o/e) 1.13, 90% interval 0.99 to 1.29.
Gene-disease validity (ClinGen):
ClinGen rates the evidence that TDP2 causes each of these diseases.
spinocerebellar ataxia, autosomal recessive 23 (autosomal recessive): Definitive.
Homologues: Orthologues: chimpanzee TDP2 (99% identical), macaque TDP2 (96% identical), guinea pig TDP2 (85% identical), pig TDP2 (85% identical), dog TDP2 (82% identical), mouse Tdp2 (65% identical), rat Tdp2 (65% identical), tropical clawed frog tdp2 (63% identical), zebrafish tdp2b (50% identical), zebrafish tdp2a (38% identical), Caenorhabditis elegans tdpt-1 (29% identical).
Diseases named in the same sentence as TDP2 in open-access papers:
TDP2 is named in the same sentence as 45 diseases in open-access papers, as found by Europe PMC text mining. Sharing a sentence is not in itself a finding about the gene and the disease. The quoted sentences say what the papers report.
Ataxia (6 papers, 2018 to 2023). Ataxia refers to impaired coordination of voluntary muscle movement. "Since TDP2 gene mutations have been linked to hereditary neurological disease in individuals with seizures, ataxia, and intellectual disability, we speculate that RAD54L2 may protect against neurological disorders." (PMID 38055822, 2023). "Here, we describe a 6-year-old patient in the United States with very similar pathology including developmental delay, epilepsy, and ataxia and in whom we identified by whole-exome and Sanger sequencing possesses the same homozygous splice site mutation in TDP2 (c.425+1G>A)." (PMID 30109272, 2018). "The identification of two inherited ataxias exhibiting exclusively neurological symptoms that are caused by mutations in TDP1 (SCAN1) and TDP2 (SCAR23) point to the potential importance of topoisomerase-mediated DNA damage in the brain." (PMID 34899270, 2021). "In addition, disturbances of the underlying repair mechanisms, which involves a coordinated action of TDP2 (tyrosyl DNA phosphodiesterase 2) with enzymes of the NHEJ repair pathway, can lead to neurological diseases associated with intellectual impairment or ataxia." (PMID 32411177, 2020). "After that, 3 cases of spastic paraplegia were found in patients (No. 2, 22, and 26) with responsible genes including (HACE1, ATL1, AP4M1), respectively, and two cases of cerebellar ataxia in patients (No. 14 and 43), whose responsible genes were SNX14, TDP2, respectively." (PMID 34540776, 2021).
hepatoma (6 papers, 2015 to 2021). "It was recently reported that RNAi-mediated Tdp2 knockdown modestly decreased DHBV CCC DNA levels in human hepatoma cells at early time points during a DNA transfection experiment." (PMID 26079492, 2015). "Using duck HBV (DHBV) in human hepatoma cells as a high-copy cccDNA model for HBV, Königer and collaborators found Tyrosyl-DNA-phosphodiesterase 2 (TDP2) as capable of releasing the viral polymerase from rcDNA." (PMID 34029994, 2021). "On the other hand, our results showed that Tdp2 gene knockout did not block CCC DNA formation during HBV infection of permissive human hepatoma cells and did not prevent intracellular amplification of duck hepatitis B virus CCC DNA." (PMID 26079492, 2015). "TDP2, though not TDP1, was able to release P protein from HBV and DHBV RC-DNA in vitro, and RNA interference-mediated depletion of TDP2 from human hepatoma cells significantly slowed down DHBV RC- to cccDNA conversion; however, cccDNA formation was not ablated even upon TDP2 knock-out." (PMID 28531167, 2017). "Furthermore, HBV PF-RC DNA, which accumulates in cultured hepatoma or non-hepatoma cells to levels higher than CCC DNA, was not significantly affected by the reduction in Tdp2 either." (PMID 26079492, 2015).
lung carcinoma (6 papers, 2012 to 2022). "In line with this, TDP2 has been shown to be overexpressed in lung cancer and knockdown of TDP2 remarkably increases lung cancer cells’ sensitivity to Top2 inhibitors, underscoring the importance of targeting TDP2 enzyme in clinic treatment." (PMID 26701725, 2016). "In the current study, we have found that ERK3, an atypical MAPK, phosphorylates TDP2 at S60 and regulates TDP2's phosphodiesterase activity, thereby cooperatively protecting lung cancer cells against Top2 inhibitors-induced DNA damage and growth inhibition." (PMID 26701725, 2016). "ERK3 phosphorylates TDP2 and promotes its phosphodiesterase activity, thereby upregualting TDP2-mediated DNA damage response and desensitizing lung cancer cells to Top2 inhibitor-induced growth inhibition." (PMID 26701725, 2016). "Activation of the MAPK signaling pathway is linked to the oncogenic factor EAPII (TDP2) and the development of lung cancer." (PMID 22748043, 2012). "Furthermore, ERK3 enhances the activity of tyrosyl DNA phosphodiesterase 2 (TDP2) in DNA damage response and increases the chemoresistance of lung cancer cells to topoisomerase‐2 inhibitors." (PMID 28079973, 2017). "Although TDP2-defective cancer cells will be hypersensitive to this type of chemotherapy, normal cells will also be hypersensitive, as illustrated in the current work by the etoposide sensitivity observed in both TDP2−/− A549 lung cancer cells and SCAR23 primary fibroblasts." (PMID 30109272, 2018). "Similarly, knock down of ERK3 (shERK3/siCtrl), TDP2 (shGIPZ/siTDP2) or both (shERK3/siTDP2) increased γ-H2AX in A549 lung cancer cells treated with etoposide." (PMID 26701725, 2016). "Indeed, similar to knockdown of TDP2 (siTDP2), knockdown of ERK3 (siERK3) greatly increased H2AX phosphorylation (γ-H2AX, a marker of DNA damage) induced by either Etoposide or Teneposide in H460 lung cancer cells." (PMID 26701725, 2016).
Intellectual disability (5 papers, 2017 to 2023). "Recent work involving clinical whole-exome sequencing identified a novel TOP2B mutation associated with intellectual disability, autistic traits, microcephaly, and developmental retardation and homozygous mutations in TDP2 have been linked with cases of intellectual disability, epilepsy, and ataxia." (PMID 29181194, 2017).
spinocerebellar ataxia, autosomal recessive 23 (4 papers, 2018 to 2024). "Mutations in TDP2, encoding tyrosyl-DNA phosphodiesterase 2, have been associated with a syndromal form of autosomal recessive spinocerebellar ataxia, type 23 (SCAR23)." (PMID 37558815, 2023). "Indeed, specific mutations in TDP2 have been linked to the human genetic disorder Spinocerebellar ataxia autosomal recessive 23 (SCAR23), which is characterized by intellectual disability, seizures, and ataxia." (PMID 39228401, 2024). "In humans, inactivation of TDP2 leads to spinocerebellar ataxia, autosomal recessive 23 (SCAR23), a neurological disease associated with epilepsy, intellectual disability, seizures, and ataxia." (PMID 31226795, 2019).
prostate carcinoma (3 papers, 2017 to 2026). A carcinoma that arises from epithelial cells of the prostate gland. "Here, we show that physiological concentrations of androgens induce several DSBs in individual human prostate cancer cells during G1 phase, and loss of TDP2 causes a five times higher number of androgen‐induced chromosome breaks in mitotic chromosome spreads." (PMID 32277721, 2020). "In this study, we examined the genotoxic effect of androgens on TDP2‐deficient human prostate cancer LNCaP cell line and mouse prostate." (PMID 32277721, 2020). "In addition to its functional roles in immune modulation and EMT, our prognostic analysis indicated that TDP2 high expression is associated with poor clinical outcomes in prostate cancer patients." (PMID 41481587, 2026). "GO pathway enrichment analysis showed that the upregulated pathways associated with TDP2 high expression cells mainly involved immune response, cell proliferation and cell differentiation, which are closely related to the growth and metastasis of prostate cancer." (PMID 41481587, 2026). "In summary, this study identifies TDP2 as a critical regulator of the tumor microenvironment in prostate cancer." (PMID 41481587, 2026). "We observed that knocking down TDP2 significantly inhibited the migration ability of prostate cancer cells, while overexpression of TDP2 significantly enhanced the migration ability." (PMID 41481587, 2026). "In this study, we aimed to characterize the functional significance of TDP2 in prostate cancer, with a focus on its impact on the immune microenvironment." (PMID 41481587, 2026). "Specifically, TDP2 overexpression in prostate cancer cells inhibited the M1 polarization of macrophages, which are typically associated with immune suppression and tumor progression." (PMID 41481587, 2026). "Lasso regression and Cox regression models highlighted TDP2 as a key prognostic biomarker, supporting its potential as a therapeutic target in prostate cancer." (PMID 41481587, 2026). "In summary, this study underscores the importance of TDP2 in shaping the tumor microenvironment in prostate cancer, particularly through its role in immune suppression and EMT." (PMID 41481587, 2026). "Consistently,the colony formation assay showed that knockdown or overexpression of TDP2 affect the total number of colonies generated of prostate cancer cells." (PMID 41481587, 2026). "The impact of the expression of TDP2 in prostate cancer cell on T lymphocytes was studied subsequently." (PMID 41481587, 2026). "Our findings provide new insights into the role of TDP2 in prostate cancer, particularly in shaping the tumor microenvironment (TME) and its involvement in immune evasion and EMT." (PMID 41481587, 2026). "Clinically, high TDP2 expression correlates with poor patient outcomes, highlighting its potential value as a prognostic biomarker and a therapeutic target in prostate cancer." (PMID 41481587, 2026). "One of the most striking findings of this study is the role of TDP2 high expression in modulating the immune response within the prostate cancer microenvironment." (PMID 41481587, 2026). "We further investigated the impact of TDP2 on the growth of prostate cancer through cell growth experiments." (PMID 41481587, 2026). "Survival analyses further demonstrated that high TDP2 expression correlated with poor clinical outcomes in prostate cancer patients." (PMID 41481587, 2026). "To reveal the important effect of TDP2 in PC cell lines, we established cell lines with either overexpression (OE) or knockdown (KD) of TDP2 in human prostate cancer cell lines (22RV1, PC3, C4-2) and a mouse prostate cancer cell line (RM-1)." (PMID 41481587, 2026). "Wound-healing and Transwell tests were used to assess the effects of TDP2 on prostate cancer cell migration." (PMID 41481587, 2026). "The work demonstrates the role of TDP2 for repairing DSBs induced by androgen in human prostate cancer cell lines and epithelial cells of the murine prostate." (PMID 32277721, 2020).
prostate carcinoma (continued). "Overall, this part of the results reveals the different roles of prostate cancer epithelial cells with high and low TDP2 expression in tumor occurrence and development, especially their differences in immunosuppression, epithelial-mesenchymal transition (EMT), and myeloid immune response." (PMID 41481587, 2026). "Thus, the results indicated that the TDP2 overexpression (OE) or knockdown (KD) prostate cancer cell line had been successfully established." (PMID 41481587, 2026). "In animal models, we further explored the impact of TDP2 on anti-tumor immunity in prostate cancer." (PMID 41481587, 2026). "Overall, our findings identify TDP2 as a key regulator within the TME and suggest its potential utility as both a prognostic biomarker and therapeutic target in prostate cancer." (PMID 41481587, 2026). "Taken together, androgens are highly genotoxic in both human prostate cancer cells and the epithelial cells of the mouse prostate particularly in the absence of TDP2." (PMID 32277721, 2020). "KEGG pathway enrichment analysis further confirmed that TDP2 high expression cells were enriched in PPAR signaling pathway and fatty acid metabolism, suggesting that lipid metabolism plays an important role in the energy metabolism and survival of prostate cancer cells." (PMID 41481587, 2026).
viral infection (3 papers, 2015 to 2020). "We have carried out further biochemical analysis of the cleavage of the RT-DNA linkage by Tdp2 and determined its role in HBV CCC DNA formation during both viral infection and intracellular CCC DNA amplification using cells with CRISPR/Cas9 mediated genetic knockout of Tdp2." (PMID 26079492, 2015).
breast carcinoma (2 papers, 2017 to 2020). "To further address the role of TDP2 in the repair of DSBs induced during transcription we depleted TDP2 in the ER-positive breast cancer cell line MCF7 using anti-TDP2 shRNA." (PMID 28794467, 2017). "Indeed, in the current study, TDP2-depleted cells exhibited reduced expression of estrogen-regulated genes in breast cancer cells, suggesting that TDP2 does indeed protect estrogen-regulated gene transcription from inhibition by TOP2-induced DSBs." (PMID 28794467, 2017).
non-small cell lung carcinoma (2 papers, 2013 to 2023). A group of at least three distinct histological types of lung cancer, including non-small cell squamous cell carcinoma, adenocarcinoma, and large cell carcinoma. "Also, it is known that Tdp2 is overexpressed in non-small cell lung carcinoma cell lines." (PMID 37895279, 2023).
ataxia telangiectasia (1 paper, 2021). Ataxia-telangiectasia is the association of severe combined immunodeficiency (affecting mainly the humoral immune response) with progressive cerebellar ataxia. "al., demonstrated a strong causal relationship between the loss of the highly-specialized DNA repair enzyme tyrosyl-DNA phosphodiesterase 2 (TDP2) and increased thymic-derived cancer predisposition in ataxia telangiectasia affected individuals." (PMID 34235080, 2021).
Fanconi anemia (1 paper, 2023). Fanconi anemia (FA) is a hereditary DNA repair disorder characterized by progressive pancytopenia with bone marrow failure, variable congenital malformations and predisposition to develop hematological or solid tumors. "Here, we describe a sibship that is homozygous for the first TDP2 missense mutation (p.Glu152Lys) and which presents with clinical features overlapping both SCAR23 and Fanconi anemia (FA)." (PMID 37558815, 2023). "Here, we describe a sibship that is homozygous for the first TDP2 missense mutation (E152K) (SNP rs754324675) identified in human neurological disease, and which presents with clinical features overlapping both SCAR23 and Fanconi anemia." (PMID 37558815, 2023). "In contrast to previously reported TDP2 patients, the current patients also exhibit short stature and skeletal abnormalities, including radial ray defects with hypoplastic thumbs, highly reminiscent of what is seen in Fanconi anemia." (PMID 37558815, 2023).
leukemia (1 paper, 2017). A malignant (clonal) hematologic disorder, involving hematopoietic stem cells and characterized by the presence of primitive or atypical myeloid or lymphoid cells in the bone marrow and the blood. "Interestingly, however, we implicate TDP2-dependent NHEJ in the formation of a rare subclass of translocations associated previously with therapy-related leukemia and characterized by junction sequences with 4-bp of perfect homology." (PMID 28794467, 2017).
poliovirus infection (1 paper, 2020). An disease or disorder caused by infection with Enterovirus C. "Viral protein production in TDP2 KO cells was also substantially reduced at 4 hpi for poliovirus infection, consistent with the observed growth kinetics delay, but reached normal levels by 6 hpi." (PMID 32023921, 2020). "Additionally, the authors reported that for poliovirus infection in the absence of TDP2, although virus titers do increase over the infection time course, they do not reach the level of those obtained from WT TDP2 MEF cells by the end of the infectious cycle." (PMID 32023921, 2020).